BRCA1 (BRCA1 DNA repair associated)
Diseases named in the same sentence as BRCA1 in open-access papers (continued):
Sharing a sentence is not in itself a finding about the gene and the disease.
breast cancer (continued). "We find that the prevalence of BRCA1 mutations is higher in TNBC compared with non-TNBC in women in whom early-onset breast cancer develops and in women with a family history of breast and ovarian cancer." (PMID 23116406, 2012). "Models developed using extended family history and genetic data, such as the IBIS model, also perform well in women considered at average risk (for example, no family history of breast cancer, BRCA1/2 mutation negative)." (PMID 23127309, 2012). "Therefore, the ability of BRCA1 to bind and ubiquitinate gamma-tubulin suppresses inappropriate centrosomal function typically observed in some breast cancers." (PMID 24278741, 2012). "We have previously reported in a study of 965 matched pairs that the total duration of breastfeeding was associated with a significant reduction in breast cancer risk among BRCA1, but not among BRCA2, mutation carriers." (PMID 22405187, 2012). "Taken together we concluded that BRCA1-IRIS expression increases in breast cancer as early as DCIS." (PMID 22511931, 2012). "Several lines of evidence presented in this study indicate that BRCA1-IRIS may act as a breast cancer oncogene that induces aggressive breast cancer when overexpressed." (PMID 22511931, 2012). "We present results which highlight that contralateral breast cancer risk in women from BRCA1/2 negative families depends on age at onset of first breast cancer, as is the case for women from BRCA1 or BRCA2 positive families." (PMID 23216834, 2012). "Previously, we reported the first Hong Kong multi-center study that comprised of 119 breast cancer patients from this region to screen for coding sequence changes in the BRCA1 and BRCA2 genes using conventional full gene DNA sequencing and identified a recurrent mutation c.3109C>T." (PMID 22970155, 2012). "This KOHBRA study showed the prevalence of BRCA1/2 mutations in high-risk breast cancer patients without family history of breast or ovarian cancer via a large multicenter nationwide cohort study." (PMID 22382806, 2012). "This is in line with our results, that is, a risk for contralateral breast cancer of 15.7% (95% CI 9.7% to 21.7%) after 5 years and 33.4% (95% CI 24.6% to 42.1%) after 10 years for women from BRCA1 positive families that developed the first breast cancer before the age of 35 years." (PMID 23216834, 2012). "The prevalence of BRCA1 and BRCA2 mutations were reported in 2.5–3.1% for sporadic breast cancers, in 19.4–42.9% for familial breast cancer patients with two or more affected first- and second-degree relatives with breast or ovarian cancers, and in 9.6–18.3% for early onset breast cancers." (PMID 22382806, 2012). "Therefore, likelihood of our samples containing BRCA1 mutations would still be minute if the probability of BRCA1 and BRCA2 mutations taken together is estimated to be 5%, equal to the proportion in total breast cancer incidence." (PMID 22937096, 2012). "The aim is to determine whether DNA-direct is an acceptable procedure for BRCA1/2 testing, in order to provide customized care to patients with breast cancer, cutting down on the period of uncertainty during this diagnostic process." (PMID 22569005, 2012). "Taken together, these findings suggest that SNPs rs2380205 at 10p15 and rs614367 at 11q13 do not modify breast cancer risk in either BRCA1 or BRCA2 mutation carriers." (PMID 22348646, 2012). "For many years, hereditary ovarian cancer was thought to be mainly, if not entirely, attributable to mutations in the BRCA1/BRCA2 breast cancer susceptibility genes." (PMID 22415235, 2012). "Members of families with BRCA1 mutations had a threefold (95%CI, 2.5 to 3.6) higher risk of contralateral breast cancer than members of families without BRCA1/2 mutations." (PMID 23216834, 2012). "In a Canadian TNBC cohort (n = 54) with an age of onset before 41 years and no familial breast cancer aggregation, five cases with mutations of BRCA1 (9%) and only one case with a mutation of BRCA2 (2%) were detected." (PMID 22666503, 2012).
breast cancer (continued). "Little is known about the contralateral breast cancer risk in women with familial breast cancer that tested negative for BRCA1 or BRCA2 mutations." (PMID 23216834, 2012). "Likewise, the age at contralateral breast cancer was also significantly lower in the BRCA1 group than the BRCA2 group (P < 0.001) and the BRCA1/2 negative group (P < 0.001)." (PMID 23216834, 2012). "In addition, epigenetic inactivation of the tumor suppressor breast cancer 1 (BRCA1) gene due to CpG island hypermethylation in breast cancer was observed." (PMID 24977105, 2012). "There was a significant reduction in breast cancer risk with breastfeeding among women with a BRCA1 but not a BRCA2 mutation." (PMID 22405187, 2012). "Although the mean age of breast cancer diagnosis of BRCA2 mutation carriers (mean age 45.7) are slightly higher than that of BRCA1 mutation carriers (mean age 40.4), the difference was not significant (p = 0.455, Wilcoxon test)." (PMID 22970155, 2012). "Overall, mutation of BRCA1 or BRCA2 genes was identified in 65 (8.6%) patients among 758 high-risk breast cancer patients without family history of breast or ovarian cancer." (PMID 22382806, 2012). "The purpose of this study is to evaluate the prevalence of BRCA1/2 mutations in non-familial breast cancer patients with high risks in Korea." (PMID 22382806, 2012). "We hypothesized that WA may target breast cancer susceptibility gene-1 (BRCA1) and heat shock factor 1 (HSF1) in breast cancer cells." (PMID 25969759, 2012). "Thus, in a BRCA1 screening study in familial breast cancer carried out in different centers in Spain, France and the United Kingdom, the missense mutation 330 A>G was independently identified in six families, all of them with Spanish/Galician ancestors." (PMID 22792365, 2012). "TBX2 gene amplification has previously been reported in aggressive BRCA1-related breast cancers." (PMID 22844464, 2012). "On the contrary, methylation is less common in estrogen receptor (ER)-negative, lymph node-negative and BRCA1-associated female breast cancer." (PMID 22765268, 2012). "In contrast, tamoxifen use did not reduce breast cancer incidence among women with inherited BRCA1 mutations." (PMID 22312502, 2011). "Brca1-deficient MMECs were not differentially sensitive to the standard breast cancer chemotherapy drugs doxorubicin, docetaxel or 5-FU." (PMID 21771338, 2011). "Recent GWAS have identified several other common breast cancer susceptibility variants which have not been investigated in BRCA1 and BRCA2 mutation carriers yet." (PMID 22053997, 2011). "Tetracycline regulated inducible expression of BRCA1 in MBR62-bcl2 breast cancer cell line increased sensitivity to paclitaxel and vincristine, by did not affect the response to cisplatin, doxorubicin, cyclophosphamide, 5-fluorouracil, or bleomycin, as determined by a clonogenic assay." (PMID 21819606, 2011). "Furthermore, treatment of MCF7 breast cancer cells with 17β-estradiol results in recruitment of ERα and p300 to the BRCA1 promoter that is, in part, mediated by AP1." (PMID 21914189, 2011). "In a matched case-control study of 472 postmenopausal women with a BRCA1 mutation, the adjusted odds ratio for breast cancer in HRT users versus nonusers was 0.58 (95% CI = 0.35 to 0.96; P = 0.03)." (PMID 22312502, 2011). "However, there is evidence in other reports that BRCA1 plays an essential role in inducing apoptosis in response to DNA-damaging agents in breast cancer cell line models." (PMID 21854619, 2011). "Furthermore, breast cancer cells with reduced BRCA1 expression due to depletion of c-Myc exhibited impaired DNA repair activity." (PMID 21668996, 2011). "However, previous studies that evaluated the expression of BRCA1 and breast cancer prognosis have demonstrated various results." (PMID 23508738, 2011). "Overall, it appears that short-term HRT use does not negate the protective effect of BSO on subsequent breast cancer risk in BRCA1/2-mutation carriers." (PMID 22312502, 2011).
breast cancer (continued). "Pathology review, with attention to a few specific morphological features of invasive breast cancers, can identify almost all BRCA1 germline mutation carriers among women with early-onset breast cancer without taking into account family history." (PMID 21343941, 2011). "The high frequency of EGFR expression in TNBCs suggests that loss of BRCA1 may be coupled, either directly or indirectly, with EGFR overexpression in breast cancer." (PMID 21396117, 2011). "The finding of a significantly higher frequency of BRCA1 c.5266dup in women with bilateral breast cancer, as well as existence of other as yet unidentified founder mutations in this population, should be further assessed in a larger well characterized high-risk cohort." (PMID 22185575, 2011). "Compared to nonhereditary breast cancer patients, BRCA1-mutation carriers are diagnosed with breast cancer at a younger age, and up to 80% of cancers occur prior to menopause." (PMID 22312502, 2011). "The current results demonstrate that despite lack of an association between a SNP and the overall breast cancer risk for BRCA1 or BRCA2 mutation carriers, residual associations exist with specific disease subtypes." (PMID 22053997, 2011). "Based on the high expression of RAD51 and RPA relative to low M1775R expression, these results suggest that M1775R may promote excessive HRR in vivo as has been suggested to occur in some breast cancers with low BRCA1 levels." (PMID 21666281, 2011). "Recently the CHEK2 1100delC variant has been found to give a 10-fold risk of male breast cancer independent of BRCA1 or BRCA2." (PMID 21949660, 2011). "BRCA1/2-associated breast cancer has not been found to be more aggressive or resistant to treatment than comparable sporadic tumors, and no study has shown an actual survival advantage for mastectomy in appropriately treated affected mutation carriers." (PMID 22295226, 2011). "Incidence of BRCA1 or BRCA2 mutations among Slovenian families with only breast cancer history (no ovarian cancer) subdivided according to the number of breast cancer cases in the family." (PMID 21232165, 2011). "Histological sections stained with haematoxylin and eosin were available for review from the breast cancer carrying the BRCA1 exon 22 deletion, and this section was found to meet the tumour morphology criteria applied to the population-based probands in this study." (PMID 21281505, 2011). "Mutations in the main high penetrance genes BRCA1 and BRCA2 are mostly found in families with multiple breast cancer cases particularly with early onset and with ovarian cancer, and may also affect breast cancer survival among the mutation carriers." (PMID 22171747, 2011). "Researchers in recent studies have pointed out that numerous signaling pathways, including the epidermal growth factor receptor, HER2, IGFR and BRCA1/2 pathways, could contribute to the malignancy of ER- breast cancer." (PMID 22113133, 2011). "Based on the evidence that several players in the ubiquitin-mediated BRCA1-dependent DDR seem to contribute to breast cancer predisposition, RNF8, UBC13 and MMS2 were considered plausible candidate genes for susceptibility to breast cancer." (PMID 21774837, 2011). "Furthermore, hsa-miR-146a, a microRNA targeting BRCA1, was the most highly up-regulated microRNA in another in vitro model of cisplatin resistance of the breast cancer cell line MCF7." (PMID 21575166, 2011). "It has been reported that in BRCA1-associated patients with a history of breast cancer, subsequent treatment with tamoxifen does not increase ovarian cancer risk." (PMID 22312502, 2011). "One other hospital-based study has evaluated the frequency of BRCA1 (but not BRCA2) mutations among unselected breast cancer cases in Greece." (PMID 22085629, 2011).
breast cancer (continued). "For this study, women without breast cancer with at least one first- or second-degree relative diagnosed with breast cancer before age 50 were eligible unless a BRCA1 or BRCA2 mutation had been identified in their family." (PMID 21896163, 2011). "BRCA1 inactivation contributes to breast cancer tumorigenesis." (PMID 21668996, 2011). "In the first report, suggesting a link between methylation of the BRCA1 promoter in PB DNA and development of breast cancer with methylated BRCA1, the authors examined methylation status of the BRCA1 promoter in tumors and PB DNA from three breast cancer patients." (PMID 22129206, 2011). "Accordingly, a common candidate breast cancer-predisposition allele in HMMR, originally identified in an Ashkenazi Jewish study, may specifically modify breast cancer risk among BRCA1 mutation carriers." (PMID 22110403, 2011). "BRCA1 and BRCA2, like other genes, have not only served as molecular markers for hereditary breast cancer risk screening but also become important indicators for breast cancer prevention, treatment, and prognosis." (PMID 21559243, 2011). "Recent evidence supports the hypothesis that BRCA1 is involved in breast cancer functions as a breast stem cell regulator." (PMID 23508738, 2011). "BRCA1 and BRCA2 are the most well-known genes predisposing to breast cancer." (PMID 21980511, 2011). "Knowledge of the role of gene fusions in BRCA1 breast cancers, however, is limited." (PMID 22032724, 2011). "Moreover, patients with germline BRCA1 mutations who develop breast cancer have a higher incidence of BM compared to germline BRCA2 carriers and non-BRCA1/2 patients." (PMID 22567347, 2011). "On the other hand, cisplatin and gemcitabine are not included in first line regimens for breast cancer, yet we found that they show therapeutic effectiveness in Brca1-deficient MMECs." (PMID 21771338, 2011). "No study has shown that BRCA1/2-associated breast cancer is more resistant to chemotherapy than are sporadic breast cancer controls." (PMID 22295226, 2011). "Similar patterns were observed for SNPs rs3803662 in TOX3/TNRC9 and rs4973768 in SLC4A7/NEK10 in which the associations were predominantly with ER-positive breast cancer for both BRCA1 and BRCA2 mutation carriers, in line with results from studies of breast cancer in the general population." (PMID 22053997, 2011). "Additionally several of the non-synonymous SNVs (66 in total) were present in genes with a previously established connection to breast cancer development through inherited genetic variations such as BRCA1 (seven SNVs) and BRCA2 (two SNVs)." (PMID 21698250, 2011). "While germline mutations in BRCA1 account for 5% of breast cancer cases, evidence suggests that epigenetic silencing of BRCA1 by promoter hypermethylation and other mechanisms may contribute to up to 30% of sporadic breast cancers." (PMID 21771338, 2011). "We observed an altered expression of BRCA1 more frequently in early onset breast cancer patients." (PMID 23508738, 2011). "BRCA1 and BRCA2 are the most well-known breast cancer susceptibility genes." (PMID 21980511, 2011). "Women who carry a BRCA1 mutation typically develop "triple-negative" breast cancers (TNBC), defined by the absence of estrogen receptor (ER), progesterone receptor and Her2/neu." (PMID 21396117, 2011). "We therefore postulate that the event of acquired defects in the BRCA1 gene could have the same effect in BRCA2 mutation carriers, as seen in sporadic breast cancers." (PMID 21958427, 2011). "Shorter repeat lengths may also provide an advantage via reduced cancer risk; in a study of women with the BRCA1 allele, shorter CAG repeat lengths within the AR gene were associated with reduced risk of breast cancer." (PMID 22151998, 2011). "Recently it has been suggested that acquisition of methylation of the BRCA1 promoter detectable in peripheral blood (PB) DNA, could give raise to development of breast cancer." (PMID 22129206, 2011).